BRIP1 (BRCA1 interacting DNA helicase 1)
Diseases named in the same sentence as BRIP1 in open-access papers (continued):
Sharing a sentence is not in itself a finding about the gene and the disease.
Fanconi anemia (124 papers, 2007 to 2025). Fanconi anemia (FA) is a hereditary DNA repair disorder characterized by progressive pancytopenia with bone marrow failure, variable congenital malformations and predisposition to develop hematological or solid tumors. "BRIP1 is associated with solid tumor risk when one copy is affected, and Fanconi anemia when both copies are affected, which leads to bone marrow failure and leukemia risk." (PMID 40766138, 2025). "Deficiency in BRIP1 and constitutional truncating variants of BRIP1 that elevate BC risk have been connected with Fanconi’s anemia." (PMID 39390525, 2024). "BRIP1 was linked to Fanconi anemia (FA), an autosomal recessive genetic disease characterized by cancer susceptibility, bone marrow failure, and multiple physical abnormalities." (PMID 36907870, 2023). "In CRC, significant associations of HR (BRCA1, BRCA2, BARD1, PALB2 and BRIP1) and Fanconi anaemia (FANCA, FANCC and FANCG) genes with TMB were identified." (PMID 37821580, 2023). "Homozygous and compound heterozygous mutations in BRIP1 have been reported as a cause of Fanconi anemia, complementation group J (OMIM:607039)." (PMID 37301908, 2023). "BRCA1 and BRCA2 are part of the BRCA–Fanconi anemia pathway, and other Fanconi genes, such as BRIP1 and RAD51C, have also been associated with an inherited risk of OC." (PMID 36555431, 2022). "Homozygous mutation of Fanconi anemia genes, including BRIP1, was reported in consanguinity family, and was responsible for bone marrow failure and severe congenital malformation." (PMID 35105904, 2022). "Deficiency in BRIP1 gene has been described as the cause for cancer-predisposing Fanconi anemia genes." (PMID 35105904, 2022). "Overall, 14.6% had mutations in BRCA1 or BRCA2, 3.3% had mutations in other BRCA–Fanconi anemia genes (BRIP1, PALB2, RAD51C, RAD51D, BARD1), and 0.4% had mutations in mismatch repair genes linked to Lynch syndrome." (PMID 32679669, 2020). "The BRIP1 gene is mutated in patients with Fanconi anemia (FA), a progressive bone marrow failure disorder, which is an autosomal recessive disease associated with an abnormal response to DNA damage." (PMID 28968953, 2017). "BRIP1 protein is mutated in the cancer prone syndrome Fanconi anemia, a disorder characterized by congenital malformations and a predisposition to the development of malignancies." (PMID 24452144, 2014). "Germline mutations in BRIP1/FANCJ are associated with Fanconi anaemia, a chromosomal instability syndrome characterised by developmental abnormalities and predisposition to cancer." (PMID 19127258, 2009). "BRIP1 deficiency has been described as the causation for cancer-predisposing Fanconi anaemia, and a recent study has identified constitutional truncating BRIP1 mutations to confer susceptibility to BC." (PMID 17504528, 2007). "Germline mutations in BRIP1 are associated with Fanconi anemia, which is a chromosome instability disorder characterized by developmental abnormalities, bone marrow failure and predisposition to cancer." (PMID 17342202, 2007). "In addition, we identified two heterozygous truncating variants in members of the Fanconi anemia (FA) pathway, which were both transmitted by the respective fathers: p.(Lys998Glufs*60) in BRIP1 (Case-40, AML) and p.Arg880* in FANCA (Case-132, medulloblastoma)." (PMID 33840814, 2021). "Examples include BRIP1, PALB2, and ataxia-telangiectasia mutated (ATM) variant alleles that produce a Fanconi anemia (BRIP1 and PALB2) or ATM phenotype when inherited in biallelic fashion, but result in only moderate cancer susceptibility as a single deleterious allele." (PMID 30120226, 2018). "Pathway analyses with the KEGG and REAC databases revealed a significant enrichment of the Fanconi anemia (FA) repair pathway, with notable genes such as BRIP1 (FANCJ), FANCI, FANCA, SLX4 (FANCP), UBE2T (FANCT), and C19orf40 (FAAP24)." (PMID 38896450, 2024).
Fanconi anemia (continued). "BRIP1 is a member of the Fanconi Anaemia gene family and functions in the double-strand break repair pathway, interacting closely with BRCA1." (PMID 39001544, 2024). "Since mutations of BRIP1 were noticed in patients of Fanconi anemia who belong to the complementation group J, BRIP1 was also named FANCJ." (PMID 36907870, 2023). "BRIP1 is involved in the Fanconi anemia DNA repair pathway and its downregulation thus supports the increase in genomic instability observed for MCF-7." (PMID 36968212, 2023). "BRIP1 (BRCA1 interacting helicase 1), also known as FANCJ (as the gene mutated in the J complementation group of Fanconi anemia) or BACH1 (BRCA1-associated C-terminal helicase), was first discovered in 2001 by its interaction with BRCA1." (PMID 37153833, 2023). "BRIP1, which belongs to the Fanconi anemia (FA) gene family, was first identified via tandem mass spectrometry through its physical interaction with BRCA1." (PMID 34408776, 2021). "Fanconi Anemia (FA) genes were mutated in 152 patients, with BRCA2 (4.0%), BRCA1 (3.7%), and BRIP1 (2.8%) mutations occurring most frequently." (PMID 34620846, 2021). "Due to their involvement in DNA repair, several groups have studied or focused their genome-wide results on variants affecting genes involved in the Fanconi anemia pathway, such as BRCA2/FANCD1, BRIP1/FANCJ, FANCC, FANCE, and REV3L/POLZ." (PMID 32585810, 2020). "Recently, the detection of pathogenic variants in Fanconi anemia DNA damage repair pathway genes, such as BRCA2, BRIP1, FANCC, and FANCE was also reported in familial CRCs34." (PMID 30850667, 2019). "In the research topic, the properties of the FANCJ (BRIP1) that affect cancer and Fanconi Anemia (FA) development have been summarized." (PMID 25729389, 2015). "Like the BRIP1 gene, individuals with biallelic mutations in PALB2 are susceptible to Fanconi anemia." (PMID 23318652, 2013). "A ChIP-chip study determined that IRF1 potentially regulates the Fanconi anemia pathway via its regulation of BRIP1 protein expression." (PMID 25893139, 2013). "Furthermore, it is noteworthy that bi-allelic inheritance of mutations in BRIP1, as well as BRCA2 and PALB2, contributes to the rare disease of Fanconi anemia, with patients being prone to both hematological and solid cancer development." (PMID 40988318, 2025). "Interestingly, germline mutation rate of members of the Fanconi anaemia family of genes (including BRCA2, PALB2, BRIP1, RAD51C, FANCA, FANCI and FANCL) was 53.4% (31/58) among the patients with germline mutations in our cohort." (PMID 32091409, 2020). "BRIP1, also known as Fanconi Anaemia Group J Protein (FANCJ) or BRCA1‐associated C‐terminal helicase (BACH1), was first identified using tandem mass spectrometry by its physical interaction with BRCA1 and also belongs to the Fanconi anaemia (FA) genes family." (PMID 32888398, 2020). "BRIP1 (BRCA1 interacting protein C-terminal helicase 1) is a protein that works with BRCA1 to repair damaged DNA and the inheritance of two mutated copies of BRIP1 causes Fanconi anaemia." (PMID 30353044, 2018). "BRIP1 acts late in the Fanconi anemia pathway, after FANCD2 ubiquitination." (PMID 29483558, 2018). "A previous IRF1 ChIP-chip study identified a number of DNA damage gene targets and this data suggests that IRF1 may regulate other proteins involved in DNA damage signaling in addition to the Fanconi anemia gene, BRIP1." (PMID 25893139, 2013). "It is interesting that most of the Fanconi anaemia genes encode proteins that form a nuclear core complex with a function of monoubiquitination of FANCD2, but FANCD1 (BRCA2) and BRIP1/FANCJ function downstream of this and they both have a more defined role in DNA damage repair." (PMID 19127258, 2009). "However, in the Fanconi anaemia pathway for DNA crosslink repair, BRIP1/FANCJ functions independently of this interaction." (PMID 19127258, 2009).
Fanconi anemia (continued). "Monoallelic germline pathogenic variants (GPVs) in five Fanconi anemia (FA) genes (BRCA1/FANCS, BRCA2/FANCD1, PALB2/FANCN, BRIP1/FANCJ, and RAD51C/FANCO) confer an increased risk of breast (BC) and/or ovarian (OC) cancer, but the role of GPVs in 17 other FA genes remains unclear." (PMID 39149814, 2024). "Likewise, biallelic BRCA1, BRCA2, BRIP1, PALB2 and RAD51C mutations lead to Fanconi anemia." (PMID 36292468, 2022). "FANCJ, originally designated BRCA1-interacting C-terminal helicase 1 (BACH1) (or BRCA1-interacting protein 1 (BRIP1)) for its interaction with the tumor suppressor BRCA1, is genetically implicated in the progressive bone marrow failure disorder Fanconi Anemia (FA)." (PMID 28594346, 2017). "After discovering that it was associated with Fanconi anemia, they screened for mutations in RAD51C in 1100 hereditary breast (HBC) and HBOC families, hypothesizing that it would be similar to BRIP1 and BRCA2 in which biallelic mutations cause Fanconi anemia and monoallelic mutations cause HBOC." (PMID 21980511, 2011). "The DNA helicase BRCA1-associated C-terminal helicase/BRCA1-interacting protein 1 (BACH1/BRIP1) is inactivated in patients with Fanconi anemia (FA); BACH1 is also known as FA complementation group (FANCJ)." (PMID 36032672, 2022). "The reversed replication forks are protected from MRE11 nuclease degradation by BRCA1, BRCA2, RAD51, and components of the Fanconi anemia (FA) complex, such as FANCA, FANCD2, and FANCJ (BRIP1)." (PMID 35806485, 2022). "BRIP1 (FANCJ/BACH1) is a DEAH helicase that interacts with the BRCT domain of BRCA1 and plays a role in HR and the repair of crosslinks by the Fanconi anaemia pathway." (PMID 34681760, 2021). "BRIP1 and FANCC belong to the Fanconi anemia pathway while MDC1 and TP53BP1 are conserved DNA damage response genes." (PMID 34220964, 2021). "FANCM is part of the Fanconi anemia group together with BRCA2, BRIP1 and PALB2 (also known as FANCD1, FANCJ, and FANCN)." (PMID 33086730, 2020). "These genes include the Fanconi anemia pathway genes: FANCA, PALB2, BRIP1, RAD51C and XRCC2 and non-Fanconi anemia genes: ATM, CHEK2, NBN, RAD50, RAD51B, and RAD51D." (PMID 28202063, 2017). "A common DNA damage network between the BRCA and Fanconi anaemia (FA) pathways has been proposed and three FA genes, FANCD1, FANCN, and FANCJ, are identical to the BRCA genes BRCA2, PALB2, and BRIP1." (PMID 24550935, 2014). "Other common genetic etiologies associated with EA/TEF include chromosomal disorders (trisomy 21, trisomy 18, trisomy 13), Feingold syndrome (MYCN), Fanconi anemia (multiple genes including FANCB, FANCC, FANCG, BRIP1) and other recurrent deletion and duplication syndromes." (PMID 36909054, 2023). "In addition, the top two enriched KEGG pathways were: 1) the Fanconi Anaemia pathway (represented by ATR, BRIP1, ERCC4, FANCC and POLH) and the FoxO signalling pathway (represented by CREBBP, NLK, PRKAA2, PRKAB1, PTEN and STK11)." (PMID 35768547, 2022). "Other defects in homologous recombination repair genes, such as EMSY, RAD51, ATM, ATR, Fanconi anemia, BARD1, BRIP1, PALB2, RB1, NF1, CDKN2A, and the suppression of BRCA1 transcriptional activation through gene methylation, are associated with homologous recombination deficiency (HRD)." (PMID 32679669, 2020). "In our efforts to understand the molecular basis of treatment response in advanced cervical cancer, besides the BRCA pathway, we also found the fanconi anemia (FA) complementation group, FANCD2, FANCL, FANCM, FANCJ/BRIP1/BACH and FANCI, to be involved in intrinsic resistance to chemo-radiotherapy." (PMID 24708616, 2014).
Fanconi anemia (continued). "Among DNA repair genes, we detected a high presence of members of the Fanconi Anemia Complementation Group (FANCC, FANCD2, FANCG, FANCA, and FANCE), which participate in homologous recombination DNA repair, and genes involved in double-strand break repair (BRCA2, BRIP1, BARD, BLM, CHEK2, and PALB2)." (PMID 30487452, 2018).
prostate carcinoma (20 papers, 2009 to 2025). A carcinoma that arises from epithelial cells of the prostate gland. "Among 743 Black prostate cancer patients, we identified 26 unique pathogenic (P) or likely pathogenic (LP) variants in 14 genes (including HOXB13, BRCA1/2, BRIP1, ATM, CHEK2, and PALB2) among 30 men, or approximately 4.0% of the patient population." (PMID 36446039, 2022). "The BRIP1 p.Arg798Ter and RAD51D p.Lys91Ilefs mutations were also shown to be a moderate-risk allele for prostate cancer and BC, respectively." (PMID 32359370, 2020).
Lynch syndrome (17 papers, 2015 to 2025). An autosomal dominant hereditary neoplastic syndrome characterized by the development of colorectal carcinoma and a high risk of developing endometrial carcinoma, gastric carcinoma, ovarian carcinoma, renal pelvis carcinoma, and small intestinal carcinoma. "Mutations in BRCA1/2, RAD51C/D, and Lynch syndrome genes were associated with a high OC risk, while mutations in BRIP1 were associated with a moderate OC risk in our study, in concordance with previous reports." (PMID 32295079, 2020). "Although HER-negative BC and HGSC are the predominant phenotypes among our families, not only were cancers associated with HBOC and Lynch Syndrome observed, but also a broader spectrum of malignancies, demonstrating an excess of gastric cases in BRIP1-positive families." (PMID 40282418, 2025). "A high OC risk has also been associated with germline mutations in RAD51C, RAD51D, Lynch syndrome genes, and STK11; a moderate OC risk with BRIP1." (PMID 32295079, 2020). "Similarly to studies on Western populations, mutations in genes other than those associated with the Lynch syndrome, including MUTYH, BRCA2, ATM, BRIP1, CDKN2A, and NF1, were identified." (PMID 39061183, 2024). "The most significant risk factor for OC development are germline pathogenic/likely pathogenic variants (GPVs) in OC predisposition genes (including BRCA1, BRCA2, BRIP1, RAD51C, RAD51D, Lynch syndrome genes, or BRIP1), which contribute to the development of over 20% of all OC cases." (PMID 38069345, 2023). "In addition to RAD51C, RAD51D and BRIP1 genes, it would be appropriate for an OC panel to also include PALB2 and Lynch Syndrome genes going forward." (PMID 34503154, 2021).
pancreatic cancer (16 papers, 2010 to 2025). "Recently, the association between BRIP1 and cancers has been reported; however, most studies were carried out on ovarian, breast, and pancreatic cancer, and most of these analyses mainly focused on identifying the mutation effects on cancers." (PMID 36907870, 2023). "Most familial pancreatic cancer is attributable to hereditary breast and ovarian cancer syndrome that results from germline mutations in BRCA1/2 genes and other genes such as ATM, BRIP1, CHEK2, RAD50, and RAD51C." (PMID 38732320, 2024). "Finally in pancreatic cancer, trials with niraparib and rucaparib in patients with HRD-mutations other than BRCA1/2, including BRIP1, are ongoing." (PMID 40988318, 2025). "MGPTs generally cover at least 10 common HR-related genes such as ATM, BARD1, BRCA1, BRCA2, BRIP1, CHEK2, NBS1 (NBN), PALB2, RAD51C, and RAD51D, all of whose germline alterations are associated with BRCAness phenotypes for predisposition to breast, ovarian, prostate, or pancreatic cancer." (PMID 35008774, 2021).
anemia (12 papers, 2009 to 2026). A reduction in the number of red blood cells, the amount of hemoglobin, and/or the volume of packed red blood cells. "BRIP1, an alternative name for BRCA1-associated C-terminal helicase (BACH1) or Fanconi anemia subtype J (FANCJ), interacts with BRCA1 through the BRCT domains at the carboxyl-terminus (Part 2)." (PMID 35008774, 2021). "The protein encoded by BRIP1 is part of the Fanconi anaemia group (FANCJ) and is involved in the repair of DNA double-strand breaks by homologous recombination." (PMID 33086730, 2020). "Several BRCA1/2 interactors, such as PALB2 (FANCN), RAD51 (FANCR), and BRIP1 (FANCJ), are also Fanconi anemia proteins." (PMID 40841483, 2026). "BRIP1, located at 17q22, is a Fanconi anaemia gene (FANCJ) that directly interacts with the BRCT domain of BRCA1 and has a role in DNA damage repair." (PMID 19935797, 2009). "Furthermore, because BRIP1 was originally identified in research on Fanconi anemia (FANCJ; OMIM #609054), the NCCN clinical practice guidelines in oncology recommend counseling BRIP1 GPV carriers about the risk of autosomal recessive conditions in their offspring." (PMID 36233090, 2022).
HBOC syndrome (12 papers, 2007 to 2025).
melanoma (10 papers, 2014 to 2025). A malignant, usually aggressive tumor composed of atypical, neoplastic melanocytes. "In the Gross Family Melanoma Registry cohort, the incidence of pathogenic germline BRIP1 variants was significantly greater in MM patients than in gnomAD, further supporting BRIP1 as a predisposing mutation." (PMID 41331641, 2025). "In light of this finding, we investigated the possibility that by blocking CtBP1/BARS functions with Comp.11, we could prevent melanoma progression by increasing the BRCA1/BRIP1-controlled DNA-Damage Response Pathway." (PMID 38711119, 2024). "For example, three cancer panel probands with BRIP1 mutations had reported clinical histories of endometrial cancer/adenomatous colon polyps, melanoma, or adenocarcinoma of the small intestine, none of which have been correlated with BRIP1 mutations at the time of writing." (PMID 24763289, 2014). "In contrast, RAS pathway mutant melanoma cells frequently rely on RAS pathway signaling to facilitate DNA repair by driving gene expression of major DNA repair factors such as BRCA2, BRIP1/FANCJ, and XRCC5." (PMID 40560846, 2025). "Moreover, patients with nonsynonymous somatic mutations in SEPT1-BRIP1 reveal poor overall survival compared to the wild type group without somatic mutations on either SEPT1 and BRIP1 in SKCM (P = 0.0012, log-rank test), offering a potential genetic interaction in melanoma." (PMID 32101536, 2020).